ADCY5 (adenylate cyclase 5)
Diseases named in the same sentence as ADCY5 in open-access papers (continued):
Sharing a sentence is not in itself a finding about the gene and the disease.
gestational diabetes (2 papers, 2015 to 2021). Carbohydrate intolerance first diagnosed during pregnancy. "g. rs11708076, rs9883204) were associated with T2D, decreased pancreatic islet ADCY5 expression, gestational diabetes, and lower birth weight." (PMID 25793868, 2015).
glioma (2 papers, 2019 to 2024). A benign or malignant brain and spinal cord tumor that arises from glial cells (astrocytes, oligodendrocytes, ependymal cells). "The results revealed that high mRNA expression of ADCY1, ADCY2, and ADCY5 were statistically related to better OS in Glioma patients with P < 0.01, compared with the low expression groups respectively." (PMID 39319137, 2024).
metabolic syndrome (2 papers, 2019 to 2020). A cluster of metabolic risk factors for CARDIOVASCULAR DISEASES and TYPE 2 DIABETES MELLITUS. "Finally, eleven CpG sites were associated with metabolic syndrome: cg08862778 (MTOR), cg11322849 (INS), cg07199894 (ULK1), cg11658986-cg04149773 (ADCY6), cg14862787-11301281 (CREB5), cg14844401-cg20300093 (ADCY5), cg01284192 (IGF1R) and cg08128650 (RELA)." (PMID 30926763, 2019).
paroxysmal choreoathetosis (2 papers, 2022 to 2025). "This group, which constitutes a separate category in paroxysmal dyskinesias, is certainly the rarest and sometimes associated with peculiar genes; the gene most involved in our sample was ADCY5." (PMID 40943684, 2025).
Choreoathetosis (1 paper, 2016). Involuntary movements characterized by both athetosis (inability to sustain muscles in a fixed position) and chorea (widespread jerky arrhythmic movements). "We suggest that exacerbations of choreoathetosis during drowsiness with prolonged sleep latency are a major clue to the presence of ADCY5 mutations." (PMID 27061943, 2016).
Encephalopathy (1 paper, 2023). Encephalopathy is a term that means brain disease, damage, or malfunction. "For example, the mRNA expression trend of NF1, RAB14, ADCY5, and RAPGEF3 in the blood is the same as that in encephalopathy, suggesting that the purpose of assessing brain state can be achieved by detecting blood-related indicators." (PMID 36923118, 2023).
generalized dystonia (1 paper, 2025). "Two unrelated patients with early‐onset mixed movement disorders, including generalized dystonia, carried the same pathogenic variant in ADCY5 (p.Arg418Trp), proven de novo in one case." (PMID 40533913, 2025).
Glucose intolerance (1 paper, 2021). Glucose intolerance (GI) can be defined as dysglycemia that comprises both prediabetes and diabetes. "In contrast, glucose tolerance was in both sexes not significantly different between the genotypes, but Adcy5–/– mice showed a trend for developing glucose intolerance under HFD." (PMID 33919448, 2021). "Regarding the area under the curve (AUC) for both diets, Adcy5–/– females exhibited a trend to develop glucose intolerance." (PMID 33919448, 2021).
Huntington disease (1 paper, 2022). Huntington disease (HD) is a rare neurodegenerative disorder of the central nervous system characterized by unwanted choreatic movements, behavioral and psychiatric disturbances and dementia. "A downregulation in ADCY5 has already been highlighted in the R6/2 mouse model of Huntington’s disease, later on in the disease." (PMID 36523271, 2022). "ADCY5 catalyses the formation of cAMP and was also downregulated in Huntington’s disease mice." (PMID 36523271, 2022).
hypertriglyceridemia (1 paper, 2022). A laboratory test result indicating elevated triglyceride concentration in the blood. "Interestingly, our results suggest an aggregate effect between the MARC1, ADCY5, and BCO1 for hypertriglyceridemia, and the effect appears to be exclusive for men." (PMID 36233117, 2022).
idiopathic dystonia (1 paper, 2021). "Seven (10%) patients had confirmed genetic diagnosis (including THAP1, ADCY5, VPS41, ATXN3, AFG3L2, KMT2B), 12 (18%) had acquired causes and the remainder had idiopathic dystonia." (PMID 34437382, 2021).
Impaired glucose tolerance (1 paper, 2021). An abnormal resistance to glucose, i.e., a reduction in the ability to maintain glucose levels in the blood stream within normal limits following oral or intravenous administration of glucose. "The inappropriate response to HFD in control mice led to significantly higher body weight, impaired glucose tolerance and insulin sensitivity only in female Adcy5–/– mice." (PMID 33919448, 2021).
inflammatory bowel disease (1 paper, 2025). A spectrum of small and large bowel inflammatory diseases of unknown etiology. "ITGA2B, F2RL3, PTGS1, and ADCY5 were associated with the platelet activation pathway, while IL18 was linked to inflammatory bowel disease (IBD) and the cytokine–cytokine receptor interaction pathways." (PMID 41157169, 2025).
insomnia (1 paper, 2022). A sleep disorder characterized by difficulty in falling asleep and/or remaining asleep. "The results of this study showed that the serum 5-HT, GABA decreased, serum DA increased in the chlorophenylalanine (PCPA) model of insomnia, and 5-HT1AR, ADCY5, and PKA in hippocampal tissue." (PMID 35990355, 2022).
invasive breast carcinoma (1 paper, 2022). A carcinoma that infiltrates the breast parenchyma. "We identify early processes and potential biomarkers, including CAMK2N1, MNX1, ADCY5, HOXC11 and ANKRD22, whose reduced expression is associated with the progression of DCIS to invasive breast cancer." (PMID 35697697, 2022).
leukemia (1 paper, 2013). A malignant (clonal) hematologic disorder, involving hematopoietic stem cells and characterized by the presence of primitive or atypical myeloid or lymphoid cells in the bone marrow and the blood. "Although large-scale screening studies of leukemias have identified ADCY5 as one of the genes that are methylated in leukemic cells, the clinicopathological impact of DNA methylation of the ADCY5 gene has not yet been clarified in human malignancies." (PMID 23544068, 2013).
nicotine addiction (1 paper, 2022). "In the network of genes annotated to the cocaine pathway (also in the nicotine addiction pathway), ADCY5, DRD1, DRD2, PPP1R1B, and protein kinase C β (PRKCB) were over-expressed in Control nursed males relative to all pig groups with exception of Control weaned females." (PMID 35627199, 2022).
pulmonary fibrosis (1 paper, 2020). Chronic progressive interstitial lung disorder characterized by the replacement of the lung tissue by connective tissue, leading to progressive dyspnea, respiratory failure, or right heart failure. "Based on above findings, we further identified key genes (ADCY1, ADCY5, ADCY8) in cAMP signal pathway and Rap1 signal pathway which were potentially regulated by the treatment of AS in BLM‐induced pulmonary fibrosis." (PMID 32548952, 2020). "To validate the effect of AS on the expression of the five key genes (ADCY1, ADCY5, ADCY8, cAMP and Rap1) in cAMP and Rap1 signal pathways in pulmonary fibrosis, we measured their expression at gene level and protein level by RT‐qPCR and ELISA experiments, respectively." (PMID 32548952, 2020).
cancer (13 papers, 2011 to 2025). A tumor composed of atypical neoplastic, often pleomorphic cells that invade other tissues. "To obtain better comprehensive knowledge of the underlying molecular mechanisms in which ADCY5 exerted its anti-cancer ability, we searched for differentially expressed target genes of ADCY5 by RNA sequencing analysis." (PMID 39319137, 2024). "High-risk genes in the model, including GPX3, AKR1C4, SPHK1and ADCY5, have been reported to promote hypermethylation, rare mutations, cancer progression, poor prognosis, and the developmental process of malignant cells in CRC patient samples or cell lines." (PMID 32953273, 2020). "ADCY5 mRNA expression in multiple cancers and their normal tissues were extracted through TCGA, HPA and CGGA databases." (PMID 39319137, 2024). "More biological investigation should be conducted in future to validate the correlation of three potential miR-146a-5p targets (PRKACB, ADCY2, and ADCY5) and miR-146a-5p in cancers." (PMID 31285693, 2019). "KEGG pathway enrichment analysis was used to detect latent regulatory mechanisms of ADCY5 and we found several cancer-related pathways participated in its carcinogenesis and progression including pathways in cancer, cAMP pathway, cGMP-PKG pathway, Wnts pathway, etc.." (PMID 39319137, 2024). "Furthermore, TCGA database indicated that ADCY5 was downregulated in nearly all cancer types, we thus investigated the clinical significance of ADCY5 mRNA expression in GBM by downloading corresponding clinical data in CGGA database." (PMID 39319137, 2024). "Considering the intimate connection between epithelia-mesenchymal transition (EMT) and cancer stemness, we also found the expression of STAT3 and KLF4 were decreased in ADCY5 overexpressing cells (P < 0.001), suggesting ADCY5 was capable of inhibiting stemness of tumor cells." (PMID 39319137, 2024). "ADCY5 has been less well studied, and the results of research knocking out the AC5 gene in mice indicated a significant reduction in angiogenesis and a rise in cancer cell apoptosis, both of which prevent cancer growth." (PMID 35832555, 2022). "ADCY5 expression was negatively related to proliferation marker MKi67 (P < 0.001) and invasion markers VIM (P < 0.001), implying ADCY5 may influence cancer cell proliferation and invasion." (PMID 39319137, 2024). "It appears that the interactomes of five out of the 17 lithium-sensitive genes (ADCY2, ADCY5, ADCY7, BPNT1, and HIPK3) do not show significant mutual enrichment with the cancer pathways explored in this study." (PMID 31114752, 2019). "Two of the genes (KIF17 and ATP8A2) showed no methylation in either cancer or matched tissues, and eight genes (EPHA4, OVOL1, UTF1, ADAM8, BOLL, FOXE3, GUCY1A2, and ADCY5) were equally methylated in the two groups." (PMID 21625442, 2011).
movement disorder (12 papers, 2015 to 2025). Neurological conditions resulting in abnormal voluntary or involuntary movement, which may impact the speed, fluency, quality and ease of movement. "Mutations in ADCY5 are responsible for a hyperkinetic movement disorder that can be preceded by episodic attacks before the movement disorder becomes persistent and is frequently misdiagnosed as dyskinetic cerebral palsy." (PMID 28511835, 2017). "Furthermore, we cannot exclude that lower activity in our Adcy5–/– mice was caused by previously reported movement disorders and contributed to the phenotype differences compared to previous Adcy5–/– models." (PMID 33919448, 2021). "accumbens and its role as a second messenger of intracellular processes may implicate a sleep disturbance as consequence of a gain of function mutation in ADCY5-associated movement disorders." (PMID 32647899, 2020). "While movement disorders in CP can show significant worsening during intercurrent infections, a clear relationship between the exacerbations of movement disorders and sleep should raise the suspicion of a misdiagnosis and lead to consider underlying ADCY5 mutations." (PMID 28511835, 2017). "We identified six new European cases with pathogenic ADCY5 mutations belonging to five different families, showing the clinical course of disease at different ages, phenotypic heterogeneity and variability of movement disorder." (PMID 28511835, 2017). "Mutations in ADCY5 represent a significant genetic cause of early-onset non-progressive hyperkinetic movement disorders, with a frequency of 11% in our series." (PMID 28511835, 2017). "With some exceptions (e.g., ADCY5-, KMT2B-, ATP1A3-related movement disorders), the number of reported patients affected by these novel genetic entities is still rather limited." (PMID 29086067, 2017).
tumor (12 papers, 2011 to 2025). "Functional studies suggest that ADCY5 acts as a tumor suppressor in GBM by restricting cell growth, invasion, and stemness, potentially modulated by epigenetic methylation." (PMID 41331166, 2025). "To assess the tumor suppressive functions, we further transfected pcDNA3.1(+)-ADCY5 expressed plasmids into U87, LN-18 and A172 cell lines." (PMID 39319137, 2024). "IHC staining indicated that ITPR1 and ADCY5 expression were decreased in tumor tissues than normal tissues." (PMID 39104385, 2024). "We identified ADCY5 as a novel tumor suppressor in GBM and its capacity of inhibiting their growth and invasion." (PMID 39319137, 2024). "ADCY5 mRNA expression was closely related to tumor grade according to CGGA databases, the higher the tumor grade, the lower the expression levels (P < 0.001)." (PMID 39319137, 2024). "Next, we examined the tumor-related function of ADCY5 in GBM as it was responsible for the endogenous downregulation." (PMID 39319137, 2024). "We further treated CRC cells with semaglutide and found that the expression of ITPR1 and ADCY5 was activated, along with inhibition of tumor cell migration." (PMID 39104385, 2024). "Taking together, these results implied ADCY5 may have prognostic value and act as tumor suppress genes in GBM." (PMID 39319137, 2024). "Interestingly, ARID1B1 and BRCA2 mutations were found to be SVZM+ tumor exclusive by deep NGS of the Heidelberg cohort as well as EPHA1, DECAF12L2, and ADCY5 by WES in the TCGA cohort." (PMID 35660939, 2022). "The adenylate cyclase 5 gene, ADCY5, is thought to be regulated by the expression of FOXP1, a tumour suppressor." (PMID 35697697, 2022). "DNA hypermethylation of the ADCY5, EVX1, GFRA1, PDE9A, and TBX20 genes resulted in reduced mRNA expression in tumorous tissue samples." (PMID 23544068, 2013). "Thus, this was the first report that ADCY5 acted as an independent prognostic factor in GBM, indicating that the potential tumor-suppressive role of ADCY5 in GBM." (PMID 39319137, 2024). "Thus, our data revealed that ADCY5 inhibited cell viability, proliferation, migration/invasion, indicating that ADCT5 was a tumor suppress gene in GBM." (PMID 39319137, 2024). "Reduced expression of the mRNAs for the ADCY5, EVX1, GFRA1 and PDE9A genes was significantly correlated with clinicopathological parameters, indicating that DNA methylation alterations, even from the precancerous stage, ultimately determine the tumor phenotype through gene silencing." (PMID 23544068, 2013).
neurological disorders (3 papers, 2016 to 2023). "From these data and a review of the other 6 kindred reported in the literature, we describe detailed clinical findings and highlight the clinical spectrum of ADCY5‐related neurological disorders." (PMID 27061943, 2016).
brain disorder (1 paper, 2022). A disease affecting the brain or part of the brain. "A representative example is shown near Adcy5, a gene in which mutation is associated with various brain disorders." (PMID 35205351, 2022).
myopathy (1 paper, 2017). A disease of the muscle in which the muscle fibers do not function properly. "A residual degree of neck hypotonia and a myopathy-like facial appearance are frequently observed in patients with ADCY5 mutations." (PMID 28511835, 2017).
ADCY5 also shares sentences with these, for which no sentence is quoted: Myoclonus (9 papers); Insulin resistance (6); cardiac hypertrophy (3); cardiovascular disease (3); colorectal cancer (3); heart disease (2); insulin-dependent diabetes (2); lipodystrophy (2); lung adenocarcinoma (2); lung carcinoma (2); neurodevelopmental disorder (2); Parkinson’s (2); schizophrenia (2); virus infection (2); Abdominal obesity (1); Arrhythmia (1); arrhythmogenic right ventricular cardiomyopathy (1); atrial fibrillation (1); cerebral palsy (1); Cirrhosis (1); citrullinemia type I (1); cocaine addiction (1); congestive heart failure (1); cyst (1); diabetic cardiomyopathy (1); diabetic retinopathy (1); Epstein-Barr virus infection (1); esophageal cancer (1); Familial Dyskinesia with Facial Myokymia (1); genetic disorders (1).
A further 17 diseases each share a sentence with ADCY5 in 1 paper.